MIAT (myocardial infarction associated transcript)
Diseases named in the same sentence as MIAT in open-access papers (continued):
Sharing a sentence is not in itself a finding about the gene and the disease.
liver fibrosis (2 papers, 2023). "The CRISPR-dCas9 system was used to activate the expression of endogenous MIAT, and the up-regulated MIAT significantly increased the hepatic fibrosis markers α-SMA, collagen I, and MMP9 of LX-2 and promoted cell proliferation." (PMID 37648688, 2023). "Owing to the up-regulation of MIAT in liver fibrosis, the level of miR-3085-5p was reduced and its target YAP was increased, resulting in the enhancement of Hippo pathway-mediated EMT process in HSCs." (PMID 36934152, 2023). "We wondered if MIAT was involved in the regulation of liver fibrosis." (PMID 37648688, 2023). "In this study, the expression of MIAT is up-regulated during liver fibrosis." (PMID 36934152, 2023). "Our data suggest that knockdown of MIAT inhibits liver fibrosis progression in vivo." (PMID 36934152, 2023). "In this study, MIAT was confirmed as a pro-fibrotic factor in liver fibrosis." (PMID 36934152, 2023). "Whether MIAT knockdown has an inhibitory effect on liver fibrosis in vivo was subsequently explored." (PMID 36934152, 2023). "Therefore, we detected MIAT expression and its pro-fibrosis effect in hepatic fibrosis cell models." (PMID 37648688, 2023). "Therefore, MIAT promotes liver fibrosis progression via miR-3085-5p/YAP/EMT pathway." (PMID 36934152, 2023). "Taken together, MIAT may be a potential biomarker for patients with liver fibrosis." (PMID 36934152, 2023). "To validate the Akt-MIAT-miR-16-TGF-β2 pathway in vivo, we treated C57 mice with hepatic fibrosis with an AKT inhibitor, MK2206, to analyze the effect of Akt on downstream MIAT and TGF-β2 gene expression in HSCs." (PMID 37648688, 2023). "However, the biological roles of MIAT in liver fibrosis are still unknown." (PMID 36934152, 2023). "Therefore, MIAT can regulate the secretion of TGF-β2 and promote the expression of liver fibrosis markers." (PMID 37648688, 2023).
lymph node metastasis (2 papers, 2017 to 2020). "Results revealed that MIAT levels were correlated with tumor size (p = 0.0035), TMN stage (p = 0.001), and lymph node metastasis (p = 0.0185) in NSCLC." (PMID 29228680, 2017).
Myocardial fibrosis (2 papers, 2021). "MIAT downregulation alleviates AF and AF-induced myocardial fibrosis through targeting miR-133a-3p." (PMID 34395566, 2021). "Additionally, the expression of MIAT shows a substantial increase in atrial tissues of AF rats while MIAT downregulation contributes to the alleviation of AF and AF‐induced myocardial fibrosis, which is evidenced by the reduced expression of fibrotic markers collagen I and collagen III." (PMID 34459123, 2021).
nasopharyngeal carcinoma (2 papers, 2021 to 2022). A carcinoma arising from the nasopharyngeal epithelium. "In this study, we demonstrated that the lncRNA MIAT/HMGB1 axis is highly upregulated in cisplatin-resistant nasopharyngeal carcinoma cell lines." (PMID 34094941, 2021).
osteoarthritis (2 papers, 2021 to 2024). A noninflammatory degenerative joint disease occurring chiefly in older persons, characterized by degeneration of the articular cartilage, hypertrophy of bone at the margins and changes in the synovial membrane. "MIAT regulates the proliferation and apoptosis of chondrocytes in osteoarthritis, and silencing MIAT can inhibit cell viability, inhibit DNA synthesis, and promote apoptosis, suggesting that MIAT is involved in the development of inflammatory diseases." (PMID 38491124, 2024). "So MIAT knockdown alleviates LPS-induced chondrocytes inflammatory injury via regulating miR-488-3p/SOX11 axis through NF-κB signaling pathway and regulating TLR4 expression in osteoarthritis." (PMID 34124371, 2021).
pancreatic cancer (2 papers, 2020 to 2021). "MIAT associates with miR-133 and contributes a role in the progression pancreatic cancer development." (PMID 32591022, 2020).
pneumonia (2 papers, 2020 to 2022). An acute, acute and chronic, or chronic inflammation focally or diffusely affecting the lung parenchyma, caused by an infection in one or both of the lungs (by bacteria, viruses, fungi, or mycoplasma.). "To explore the molecular mechanism of MIAT in LPS-induced pneumonia, we used miRanda database and found a potential binding between MIAT and miR-147a." (PMID 33318298, 2020). "Therefore, we speculate that lncRNA MIAT may participate in the progression of pneumonia by regulating inflammatory response." (PMID 33318298, 2020).
prostate carcinoma (2 papers, 2017 to 2022). A carcinoma that arises from epithelial cells of the prostate gland. "In order to further study the mechanism of lncRNA MIAT in prostate cancer, we predicted and verified the binding sites between lncRNA MIAT and miR-361-3p." (PMID 36245704, 2022). "lncRNA MIAT was upregulated, while miR-361 was downregulated in the prostate cancer tissues and Du145 cells." (PMID 36245704, 2022). "Similarly, lncRNA MIAT expression was increased in prostate cancer cells Du145 and miR-361-3p expression was decreased." (PMID 36245704, 2022). "Therefore, we assumed that lncRNA MIAT may affect the proliferation and apoptosis of prostate cancer cells by regulating miR-361-3p/CCAR2, and play a certain role in prostate cancer." (PMID 36245704, 2022). "In conclusion, we found that lncRNA MIAT knockdown inhibited cell proliferation and induced apoptosis in prostate cancer through miR-361-3p/CCAR2 axis and participated in prostate cancer, which would provide new targets for the treatment of prostate cancer." (PMID 36245704, 2022).
renal carcinoma (2 papers, 2021 to 2024). A carcinoma arising from the epithelium of the renal parenchyma or the renal pelvis. "The TCGA database analysis revealed the differential expression of 7 DElncRNAs namely GAS6-AS1, MIAT, LINC00921, MMP25-AS1, C22orf34, MIR34AHG, and MIR4435-2HG in 4 distinct pathological subtypes of renal cancer." (PMID 39213211, 2024).
Stroke (2 papers, 2019). Sudden impairment of blood flow to a part of the brain due to occlusion or rupture of an artery to the brain. "Moreover,MIAT was recently found to be up-regulated in patients withischemic stroke, a disease that shares a similar pathogenesis with CAD." (PMID 31188931, 2019).
type 2 diabetes (2 papers, 2016 to 2018). "Circulating levels of LIPCAR, SENCR and MIAT were further evaluated in a validation study of 30 men with well-controlled type 2 diabetes." (PMID 27874027, 2016). "In contrast, levels of MIAT were higher in type 2 diabetes patients as compared with healthy volunteers (P < 0.050)." (PMID 27874027, 2016). "Type 2 diabetes patients in the fourth quartile of circulating MIAT or SENCR levels showed a higher LVMV-ratio than those in lower quartiles (P < 0.050)." (PMID 27874027, 2016). "Second, the direct association of LVMV-ratio with circulating MIAT and SENCR, even after adjusting for possible confounding factors, indicates that both lncRNAs are independent predictors of LV remodelling in patients with stable type 2 diabetes." (PMID 27874027, 2016). "A close correlation between circulating H19, HOTAIR, MIAT and SENCR levels was also observed in the type 2 diabetes group." (PMID 27874027, 2016). "Compared to control subjects, expression levels of lncRNAs in PBMCs from type 2 diabetes patients showed significantly (p < 0.05) increased levels of HOTAIR, MEG3, LET, MALAT1, MIAT, CDKN2BAS1/ANRIL, XIST, PANDA, GAS5, Linc-p21, ENST00000550337.1, PLUTO, and NBR2." (PMID 30139387, 2018). "Compared to control subjects, expression profiling of lncRNAs in PBMCs from type 2 diabetes patients showed significantly (p < 0.05) increased levels of HOTAIR, MEG3, LET, MALAT1, MIAT, CDKN2BAS1/ANRIL, XIST, PANDA, GAS5, Linc-p21, ENST00000550337.1, PLUTO, and NBR2." (PMID 30139387, 2018). "Our data demonstrate that circulating levels of LIPCAR and MIAT or SENCR may constitute novel biomarkers of LV diastolic function and remodelling, respectively, in patients with well-controlled type 2 diabetes." (PMID 27874027, 2016).
adenovirus infection (1 paper, 2019). "Conversely, the over-expression of MIAT by adenovirus infection efficiently increased ox-LDL-induced CD47 expression." (PMID 30755588, 2019).
astrocytoma (1 paper, 2017). "GBM also displayed statistically lower HAR1A and MIAT expression as compared with oligodendroglioma (P =0.002 and P =0.008), oligoastrocytoma (P =0.016 and P =0.044), and astrocytoma (P =0.009 and P =0.054)." (PMID 29108264, 2017).
Autoimmunity (1 paper, 2022). The occurrence of an immune reaction against the organism's own cells or tissues. "Given the positive regulation of proinflammatory genes (e.g., IL17, CXCL13, and CSF2) by MIAT, we were interested in investigating the significance of MIAT in autoimmunity." (PMID 35784351, 2022).
benign gynecologic tumors (1 paper, 2024). "Targeting MIAT, which sponges the pro-fibrotic miR-29 family, is an effective therapy for fibroids by reducing cell proliferation and thereby, tumor growth and accumulation of ECM, which is a hallmark of these benign gynecologic tumors." (PMID 38817011, 2024).
cardiomyopathy (1 paper, 2021). A disease of the heart muscle or myocardium proper. "MIAT expression was aberrantly elevated in cardiac diseases like cardiomyopathy and cardiac fibrosis, suggesting the potential functionality of MIAT in cardiac disorders." (PMID 33819189, 2021).
Cerebral ischemia (1 paper, 2021). Restriction of arterial blood supply to the brain associated with insufficient oxygenation to support the metabolic requirements of the tissue. "Moreover, MIAT also acts to sponge miR‐204‐5p in the MIAT/miR‐204‐5p/HMGB1 axis in cerebral ischemia." (PMID 33340430, 2021).
cervical cancer (1 paper, 2020). A primary or metastatic malignant neoplasm involving the cervix. "The low expression of MIAT was characterized in cervical cancer, which associated with relatively poor prognosis." (PMID 32549789, 2020). "Noting worthily, the molecular mechanism underlying low-expression of MIAT in cervical carcinoma was still to be investigated in future." (PMID 32549789, 2020). "High expression of MIAT significantly associated with better prognosis in cervical cancer patients." (PMID 32549789, 2020). "Our study characterized the anti-tumor property of MIAT in cervical cancer and elucidated its competitively regulation of CDKN1B with miR-150." (PMID 32549789, 2020). "Here we set out to determine the expression status of MIAT and seek to elucidate its mechanistic linkage to cervical cancer." (PMID 32549789, 2020). "Ectopic expression of MIAT in cervical cancer cells remarkably suppressed cell proliferation, anchorage-independent growth." (PMID 32549789, 2020). "Our data unambiguously demonstrated that miR-150-5p predominately contributed to anti-tumor activity of MIAT in cervical cancer." (PMID 32549789, 2020). "Consistent with this, we first characterized aberrant low-level of MIAT in cervical carcinoma both in vivo and in vitro." (PMID 32549789, 2020). "Mechanistically, we elucidated that MIAT functioned as ceRNA against miR-150-5p, and MIAT abundance inversely correlated to endogenous miR-150-5p in cervical carcinomas." (PMID 32549789, 2020). "Our data clearly demonstrated that ectopic overexpression of MIAT significantly inhibited cell proliferation and anchorage-independent growth in cervical carcinoma cell lines." (PMID 32549789, 2020). "First, the relative expression of MIAT in cervical carcinoma was determined by q-PCR in 21 pairs of cervical tumors and adjacent benign tissues." (PMID 32549789, 2020). "Moreover, Kaplan–Meier cumulative survival curve exhibited more favorable outcome in MIAT-high cervical cancer group (with median survival time 42 months v.s 15 months in MIAT-low group), which consolidated the tumor suppressor role of MIAT in vivo." (PMID 32549789, 2020). "Ectopic expression of MIAT inhibited malignant growth of cervical cancer both in vitro and in vivo." (PMID 32549789, 2020). "Mechanistically, MIAT regulated CDKN1B expression via competition with miR-150, and miR-150-inhibition directly suppressed cervical cancer cell growth." (PMID 32549789, 2020). "However, the expression pattern and involvements of MIAT in cervical cancer are not fully investigated." (PMID 32549789, 2020). "In summary, here we identified the anti-tumor property of MIAT through endogenously competing for miR-150 in regulation of CDKN1B, which consequently contributed to our comprehensive understanding of mechanistic involvements of long non-coding RNA in cervical carcinoma." (PMID 32549789, 2020).
cervical tumors (1 paper, 2020). "MIAT was significantly lower in most of cervical tumors in comparison with normal control, which indicated the potential anti-tumor properties of MIAT in this disease." (PMID 32549789, 2020).
Cirrhosis (1 paper, 2023). A chronic disorder of the liver in which liver tissue becomes scarred and is partially replaced by regenerative nodules and fibrotic tissue resulting in loss of liver function. "Interestingly, MIAT expression in patients with cirrhosis was positively correlated with Col1A1 mRNA expression (r = 0.7334, p < 0.001)." (PMID 36934152, 2023).
COVID-19 (1 paper, 2021). A disease caused by infection with severe acute respiratory syndrome coronavirus 2. "The result obtained for the time points and type of IFN treatment reduced expression of EGOT, GABPB1-AS1, IDI2-AS1, LINC00312, LINC00662, MIAT, PVT1, SNHG7; expression of these lncRNA was increased in SARS-CoV-2 infected cells or in the tissue obtained from COVID-19 patients." (PMID 34940755, 2021).
endothelial dysfunction (1 paper, 2018). In vascular diseases, endothelial dysfunction is a systemic pathological state of the endothelium (the inner lining of blood vessels) and can be broadly defined as an imbalance between vasodilating and vasoconstricting substances produced by (or acting on) the endothelium. "Interestingly MIAT is involved in endothelial dysfunction as well, which is frequently observed in ME/CFS." (PMID 30119681, 2018).
ganglioneuroma (1 paper, 2021). A benign neuroblastic tumor of the sympathetic nervous system that occurs in childhood. "We found a significantly higher MIAT positivity in high-risk NBL than in samples of lower risk or benign tumors, such as ganglioneuroma (p < 0.01)." (PMID 33806217, 2021).
head and neck squamous cell carcinoma (1 paper, 2022). A squamous cell carcinoma that arises from any of the following anatomic sites: lip and oral cavity, nasal cavity, paranasal sinuses, pharynx, larynx, and salivary glands. "However, the role of MIAT in head and neck squamous cell carcinoma has not been reported." (PMID 36230580, 2022).
Hodgkins lymphoma (1 paper, 2016). A heterogeneous group of malignant lymphoid neoplasms of B-cell origin characterized histologically by the presence of Hodgkin and Reed-Sternberg (HRS) cells in the vast majority of cases. "In the present study, we showed MIAT upregulation in malignant mature B cells including established cell lines of CLL and non-Hodgkin lymphoma origin as well as primary leukemic cells obtained from CLL patients." (PMID 27527866, 2016).
Huntington disease (1 paper, 2018). Huntington disease (HD) is a rare neurodegenerative disorder of the central nervous system characterized by unwanted choreatic movements, behavioral and psychiatric disturbances and dementia. "Some lncRNAs, including myocardial infarction associated transcript (MIAT), metastasis-associated lung adenocarcinoma transcript 1 (MALAT1), and nuclear enriched abundant transcript 1 (NEAT1), influence neurodegenerative diseases such as Huntington’s disease and AD." (PMID 30469430, 2018).
laryngeal squamous cell carcinoma (1 paper, 2022). A squamous cell carcinoma that arises from the larynx. "Consistently, recent literature confirmed the direct binding between MIAT and miR-613 in laryngeal squamous cell carcinoma cells and that MIAT can function as a sponge of miR-613 to downregulate its expression." (PMID 35347106, 2022).
lentivirus infection (1 paper, 2021). Virus diseases caused by the Lentivirus genus. "Accordingly, MIAT silencing by shRNA lentivirus infection increased BTZ sensitivity in vitro by negatively regulating miR-29b, leading to control over the expression of miR-29b target genes." (PMID 34771679, 2021).
Lyme disease (1 paper, 2016). Lyme disease (named after the towns in the USA where the disease was first identified) is a bacterial infection caused by Borrelia burgdorferi. "When all of the time points were combined, a total of four different DEGs overall were identified in Lyme disease patients with persistent symptoms (non-PTLDS and/or PTLDS) compared to those with resolved disease, i.e., MIAT, CCDC163P, ZNF266, and GPR15." (PMID 26873097, 2016).
myocardial ischemia (1 paper, 2017). A disorder of cardiac function caused by insufficient blood flow to the muscle tissue of the heart. "To investigate if MIAT up-regulation in MI can produce any consequences on the pathological process or is merely a consequence of myocardial ischemia, we assessed the effects of MIAT knockdown on cardiac function in the context of MI." (PMID 28198439, 2017).
non-Hodgkin lymphoma (1 paper, 2016). Distinct from Hodgkin lymphoma both morphologically and biologically, non-Hodgkin lymphoma (NHL) is characterized by the absence of Reed-Sternberg cells, can occur at any age, and usually presents as a localized or generalized lymphadenopathy associated with fever and weight loss. "Although further study by applying different approach is needed to determine whether the anti-apoptotic function of MIAT is conserved in CLL, CLL cells are generally considered as low-grade non-Hodgkin lymphoma particularly in advanced stage." (PMID 27527866, 2016).
paroxysmal AF (1 paper, 2021). "Furthermore, the expression of MIAT was potently different in EVs from serum samples of patients with paroxysmal AF, persistent AF, and permanent AF, with the highest expression observed in the EVs from serum samples of permanent AF patients." (PMID 34459123, 2021).
primary immunodeficiency (1 paper, 2022). "Besides, among the KEGG pathways, primary immunodeficiency-related pathway was the most significantly associated with MIAT, suggesting that MIAT is coexpressed with genes associated with immune-related diseases." (PMID 35784351, 2022).
psoriasis (1 paper, 2022). An autoimmune condition characterized by red, well-delineated plaques with silvery scales that are usually on the extensor surfaces and scalp. "Interestingly, a reanalysis of published data showed that MIAT was expressed in T cells from the synovium of RA patients and the skin lesions of psoriasis patients." (PMID 35784351, 2022).
ulcerative colitis (1 paper, 2021). An inflammatory bowel disease involving the mucosal surface of the large intestine and rectum. "This corroborates a recent study that found that cinnamaldehyde can ameliorate ulcerative colitis through the suppression of Th17 cells and the regulation of MIAT." (PMID 34249084, 2021).
viral infection (1 paper, 2018). "Consistently, both THP-1 and KALS1 cell lines showed higher expression levels of MIAT and ZEB1 after stimulation of poly (I:C), a synthetic analog of double strand RNA representing active viral infection, a potential trigger of ME/CFS." (PMID 30119681, 2018).